SPP1 (secreted phosphoprotein 1)
Diseases named in the same sentence as SPP1 in open-access papers (continued):
Sharing a sentence is not in itself a finding about the gene and the disease.
tumor (continued). "SPP1+ macrophages exhibited pronounced transcriptional alterations at stage IV, implying that their functional reprogramming may be linked to tumor metastasis." (PMID 41246350, 2025). "However, we observed that patients with low CS scores exhibited a higher abundance of SPP1+ TAMs, which are associated with an immunosuppressive microenvironment and tumor progression." (PMID 40230843, 2025). "Notably, SPP1+ macrophages, a subset that primarily mediates protumor effects, considerably declined after vaccine, further supporting the functional switch of tumor-associated macrophages." (PMID 39888994, 2025). "Additionally, another study on NSCLC has linked SPP1+ TAMs to pro‐angiogenic functions, further underscoring their role in tumour progression." (PMID 40395129, 2025). "In the context of cancer, SPP1 is closely associated with tumor progression and prognosis." (PMID 41391064, 2025). "Thus, SPP1 emerges as a central regulator of tumor malignancy by orchestrating pathogenic ECM remodeling." (PMID 41293726, 2025). "Among these, SPP1+ tumor-associated macrophages (TAMs) have been frequently reported." (PMID 40376263, 2025). "SPP1 is also closely associated with tumor development and metastasis." (PMID 40196737, 2025). "Notably, SPP1+ TAMs were found to be enriched in tumor cores and associated with poor prognosis in HCC." (PMID 40725473, 2025). "Considering the strong association between eCAFs and SPP1+ macrophages within their respective cellular subpopulations and their relevance to prognosis and tumor progression, researchers performed pseudotime analysis to further explore their intrinsic lineage evolution processes." (PMID 40657391, 2025). "High SPP1 expression may have therapeutic implications, as immune exclusion correlates in the tumour microenvironment with cancer associated fibroblasts resulting in resistance to immune checkpoint therapy." (PMID 40348815, 2025). "Interestingly enough, SPP1 expression was inversely correlated to PECAM1 (encoding for the endothelial marker CD31) in tumor and healthy LUAD TCGA samples." (PMID 40028673, 2025). "Notably, SPP1-associated signaling pathways were markedly dysregulated in tumor tissues, underscoring the importance of TPS-driven signaling networks in shaping the HCC immune microenvironment." (PMID 41268553, 2025). "The increased expression of SPP1 may originate from both tumor cells and tumor-associated macrophages (TAMs)." (PMID 41345544, 2025). "SPP1+ macrophages have been implicated in promoting tumor progression and immune escape." (PMID 40406147, 2025). "Macrophages1 (CXCL8hiIL1Bhi), which they speculated may be SPP1+ TAMs, were predominantly present in EC samples, expressing cytokines associated with tumor cell proliferation, invasion, and metastasis signaling pathways." (PMID 39229264, 2024). "Finally, targeting SPP1 in tumor-associated macrophages through inhibition led to a shift towards a favorable phenotype." (PMID 39691723, 2024). "Importantly, a distinct subset of tumor‐associated macrophages (TAMs) characterized by exclusive expression of phosphoprotein 1 (SPP1) is discovered." (PMID 39236316, 2024). "Notably, SPP1 mRNA expression was strongly linked to tumor-associated macrophages (TAMs), particularly the M2 macrophage subtype, indicating a substantial association in the context of TNBC." (PMID 39727934, 2024). "Notably, SPP1’s association with cancer is profound, with its pivotal role in tumor invasion, metastasis, apoptosis, and angiogenesis documented extensively." (PMID 38248779, 2024). "Among these, SPP1 has been implicated in tumour bone metastasis." (PMID 38445456, 2024). "In addition, expression of SPP1 is closely associated with tumor cell evolution and microenvironmental reprogramming." (PMID 38664521, 2024). "Furthermore, SPP1 tumor-associated macrophages (TAMs) and proliferating cancer cells were colocalized, and stromal cells, regulatory T cells, terminally exhausted T cells, and C1QC TAMs were also colocalized." (PMID 39858416, 2024).
tumor (continued). "SPP1+ Mo-Mp demonstrated a pro-inflammatory and bone-resorbing phenotype in RA synovia, but seemed to play an immunosuppression role by interacting with cancer-associated fibroblasts in particular tumor microenvironment." (PMID 38601143, 2024). "SPP1 regulates host immunity during the chronic inflammation associated with cancer development and is capable of promoting proliferation and preventing the apoptosis of tumor cells." (PMID 39616302, 2024). "SPP1 functions in tumor-associated inflammation and can promote tumor progression." (PMID 39616302, 2024). "Additionally, SPP1 expression was closely linked to tumor-associated macrophages (TAMs), specifically M2 macrophages, highlighting a significant association in TNBC." (PMID 39727934, 2024). "Interestingly, one group of LAMs displayed elevated expression of SPP1, which has been reported to be secreted by tumor-associated macrophages (TAMs) to promote cancer progression." (PMID 38311726, 2024). "Considering the distribution of relevant cells near SPP1+ macrophages, this hypoxia might be mostly caused by proliferating tumor cells due to their high proliferation and high oxygen‐consumption behaviors in the leading‐edge area." (PMID 39716897, 2024). "Additionally, key immune cell subpopulations were found to be associated with tumor progression or metastasis, including the SPP1+ TAM enriched in CRC liver metastasis." (PMID 38649887, 2024). "The most significantly upregulated gene in the gene expression signature was secreted phosphoprotein 1 (SPP1), which is well known to be involved in the regulation of many tumor-associated biological processes, including tumorigenesis, tumor progression, and the tumor immune microenvironment." (PMID 39409192, 2024). "Additionally, we analyzed interactions among the key immune cells and evaluated the effects of inhibition of the key gene, SPP1 in tumor-associated macrophages." (PMID 39691723, 2024). "In addition to that, there was the immune barrier structure located near the tumor boundary, which was a spatial niche composed of SPP1+ macrophages and cancer-associated fibroblasts." (PMID 37313417, 2023). "Furthermore, SPP1+ SAMs share an overlapping transcriptome with TREM2+ tumor-associated macrophages (TAMs), lipid-associated macrophages (LAMs), and disease-associated microglia (DAM) – hence lack specific functionality for tissue fibrosis." (PMID 37706477, 2023). "Meanwhile, macrophages and dendritic cells within BM demonstrated more pro-tumoral and anti-inflammatory effects, represented by distinct distribution and function of SPP1+ and C1Qs+ tumor-associated microphages, and inhibited antigen presentation capacity and HLA-I gene expression, respectively." (PMID 36671569, 2023). "SPP1+ TANs displayed a gene expression signature similar to pro-angiogenic tumour-associated macrophages (TAMs) and were therefore predicted to play a key role in tumour angiogenesis, thus termed angiogenic TANs." (PMID 37534829, 2023). "mCAFs, constituting an aggressive CAF subset, promoted tumor cell invasion, activated endothelial cells to trigger angiogenesis, and synergized with SPP1+ tumor associated macrophages to induce tumor progression, ultimately decreasing the overall survival of patients with HPSCC." (PMID 37853464, 2023). "Interestingly, M2-like macrophages associated with SPP1 are discovered in a variety of cancers and located in the tumor core tissue." (PMID 38274828, 2023). "Tumor microenvironment genes linked to ocular angiogenesis include Spp1, Csf1, and Cxcr4." (PMID 37858232, 2023). "Importantly, previous studies have reported that a special subtype of tumor-associated macrophages (TAM) with strong SPP1 expression presents immunosuppressive features and is positively correlated with EMT markers." (PMID 37090726, 2023). "Moreover, macro-C4 expressed high levels of secreted phosphoprotein 1 (SPP1), a marker of M2 macrophages associated with tumor angiogenesis." (PMID 36725186, 2023).
tumor (continued). "Moreover, SPP1 protein level was further investigated by immunohistochemistry, and the association between SPP1 and tumor-infiltrating immune cells was explored." (PMID 36959981, 2023). "Susceptibility of multiple patient‐derived BM‐NSCLCs to representative targeted agents is altered and secretion of serpin E1, interleukin‐8, and secreted phosphoprotein 1, which are associated with tumor aggressiveness and poor clinical outcome, is increased in tri‐culture." (PMID 35657027, 2022). "In addition, after PRI-2191 treatment, an increased expression of the Spp1 gene (encoding OPN) was observed in young 4T1 tumor-bearing mice." (PMID 35954312, 2022). "However, genes associated with tumor metastasis and tumor cell proliferation (SPP1, GSTA1, MAL2, and MGST1) were found to be highly expressed in LUSC1, LUSC2, LUSC4 samples." (PMID 35899203, 2022). "Particularly, the ubiquitous presentation of endothelial-to-mesenchymal transition CAF, which may interact with proximal SPP1+ tumor-associated macrophages, is implicated in endothelial-to-mesenchymal transition and survival stratifications." (PMID 36333338, 2022). "The most recent study indicated that tumor cell-intrinsic SPP1 could promote macrophages to M2-like tumor-associated macrophages (TAMs) by mediating the crosstalk between HCC malignant cells and macrophages." (PMID 35958556, 2022). "In addition, SPP1+ tumor-associated macrophages (TAMs) were colocalized with proliferating cancer cells, which is consistent with a recent study in CRC." (PMID 36313703, 2022). "And to date, almost all studies on the prognostic and diagnostic value of SPP1 were based on the SPP1 levels in peripheral blood, while the SPP1 in the tumor microenvironment is of high levels and its effect on the tumor is theoretically more direct." (PMID 35593388, 2022). "Moreover, SPP1 expression was dramatically upregulated in tumor-associated macrophages (TAMs) following ICBs, and SPP1+ TAMs correlated with adverse clinical outcomes in an independent cohort of 264 patients with ICC." (PMID 35558087, 2022). "Through bulk RNA sequencing (bulk RNA-seq) and immunohistochemistry (IHC), we found that SPP1 was highly expressed in GC, and high levels of SPP1 were associated with macrophage infiltration, an advanced tumor stage, and higher mortality for advanced GC patients." (PMID 36612160, 2022). "Interestingly, simultaneous knockdown of SPP1 in 4T1 tumor cells caused a complete abrogation of metastasis." (PMID 34832904, 2021). "Besides, a recent study based on single-cell analysis showed that SPP1+ TAMs were associated with tumor angiogenesis in various cancer types." (PMID 34676217, 2021). "Interestingly, SPP1 overexpression was positively associated with tumor size (p=0.035), histological grade (p=0.003), and nodal status (p=0.002) of GAC patients." (PMID 34367279, 2021). "Third, although the macrophage-mediated SPP1/CD44 signaling has been implicated in regulating the evolution of MES-like tumor cells in this study, the precise mechanisms driving the transition from OPC/NPC-like to MES-like cells have not been investigated, which need to be addressed in the future." (PMID 34805184, 2021). "In addition, SPP1 is a cardinal mediator of tumor-associated inflammation and facilitates metastasis." (PMID 35096608, 2021). "SPP1 expression was higher in LUAD tumor tissues and in people with EGFR mutation." (PMID 34178613, 2021). "SPP1 expression was higher in EGFR-mutated tumor samples than in wild-type samples (P = 0.017)." (PMID 34178613, 2021). "Osteopontin is encoded by the secreted phosphoprotein 1 (SPP1) gene and is expressed by a variety of cells, including epithelial cells and cells from the tumor microenvironment, tumor stroma and the inflammatory niche (such as neutrophils, natural killers, leucocytes, macrophages and T cells)." (PMID 34680488, 2021).
tumor (continued). "Epigenetic modification of genes is an important cause of abnormal gene expression in tumor cells, so we strived to know whether the abnormal expression of SPP1 is also caused by changes in epigenetic modification." (PMID 33996808, 2021). "Focusing on myeloid cell populations in CRC, other groups discovered novel SPP1 (secreted phosphoprotein 1) expressing tumor association macrophage (TAM) that could play critical roles in CRC tumorigenesis." (PMID 34778231, 2021). "Therefore, we evaluated the potential significance of OCT4- and SPP1-transcript variants in human clinical tumour tissues." (PMID 32503462, 2020). "If there is an association between SPP1 and lower ER signalling, patients with an ER+ tumour that expresses higher levels of SPP1 could theoretically be less responsive to anti-oestrogen treatment." (PMID 31996744, 2020). "For example, our computational analysis showed that the increased expression of SFN and SPP1 were associated with higher tumor grades and worse survival outcomes, indicating that SFN and SPP1 might act as oncogenes in HCC." (PMID 33221766, 2020). "Moreover, the association of SPP1 level with the immune cell marker sets implicated that SPP1 was involved in the regulation of tumor immunity." (PMID 33324676, 2020). "SPP1 participates in the regulation of tumor-associated angiogenesis and inflammation." (PMID 33381538, 2020). "Similarly, osteopontin (which is encoded by SPP1) is correlated significantly with tumor metastasis and a poor prognosis in cancers." (PMID 33362844, 2020). "Additionally, we investigated the association of YBX1, G3BP1 and SPP1 expression with several clinical parameters including gender, age, tumor size, TNM stage and Fuhrman grade." (PMID 31481087, 2019). "Additionally, we identified Iroquois Homeobox 2 (IRX2) as a master regulator for the secretion of SPP1-encoded osteopontin, a stromal driver for tumor growth that is overexpressed by both RS and SIPS fibroblasts." (PMID 28105936, 2016). "Common single nucleotide polymorphisms (SNPs) such as -443C>T (rs11730582), -156G>GG (rs17524488) and -66T>G (rs28357094) may result in increased expression of SPP1 gene and tumor risk." (PMID 26267616, 2015). "However, SPP1 knockdown caused a significant reduction in tumour spheroid size (n = 40, P = 0.0001) in all MPNST cell lines tested." (PMID 25884485, 2015). "The expression of SPP1 is strongly associated with tumorigenesis and tumor metastasis." (PMID 24758329, 2014). "Indeed, recent studies indicate that the hypoxic tumor microenvironment fosters an interplay among its cellular constituents—including cancer cells, cancer-associated fibroblasts, Tregs, MDSCs, and macrophages—that promotes SPP1 macrophage differentiation." (PMID 41425545, 2025). "Myeloid cells were subclustered into monocyte, Tumor-associated macrophage (TAM) including SPP1+ TAM, C1Qs+TAM, HSPs+ TAM, ACP5+ TAM, and CCL5+ TAM, classical dendritic cell (cDC) encompassing cDC, CD1A+ DC, LAMP3+ DC and PCLAF+ DC, plasmacytoid DC (pDC) as well as unknown subpopulations." (PMID 40904511, 2025). "Notably, Vegfa macrophages and Proinflammatory macrophages exhibited downregulation of tumor angiogenesis and protumorigenic genes (e.g., Cxcl3, Cxcl1, S100a8, SPP1) and upregulation of immune cell recruitment‐associated genes (e.g., Cxcl9, Ccl5, Ccl8) in mRNA‐treated groups." (PMID 39761175, 2025). "Interestingly, a recent study showed that macrophages infiltrated in the TME require SPP1 to maintain M2-like features, which in turn induces Tumor-associated macrophages (TAMs) to derive more SPP1, ultimately creating a positive feedback loop with pro-tumorigenic effects." (PMID 38898490, 2024). "Therefore, the combined use of CgA (a broad indicator of neuroendocrine cell activity and tumor burden) and SPP1 (associated with aggressive tumor behavior and metastasis) may provide additional benefits for the diagnosis of GEP-NENs." (PMID 38835066, 2024).
tumor (continued). "Moreover, upregulation of SPP1 on B cells in cancer is associated with poor prognosis and may be a potential target for anti-tumor therapy." (PMID 39796714, 2024). "Notably, SPP1+ tumor-associated macrophages exhibited a poor prognosis." (PMID 39440065, 2024). "Through single-cell transcriptomic sequencing, we discovered that the monocyte_C02 subpopulation is more prevalent in right-sided colorectal cancer, and its highly expressed genes, such as CXCL8, TNFAIP6, CXCL3, and SPP1, may be implicated in tumor growth promotion." (PMID 38711918, 2024). "Elevated SPP1 expression might be linked to tumor recurrence or progression." (PMID 38275392, 2023). "Furthermore, we identified SPP1 as the specific signaling pathway involved in the intercellular crosstalk between tumor cells and CD8+ T cells associated with Ero1aWT tumors; however, the rigid cell-to-cell interactions within the ERO1A-associated TME remodeling require more functional studies." (PMID 37769655, 2023). "Together, our results suggested that POSTN+ CAFs and SPP1+ macrophages were closely associated at the tumour stroma, which may be critical in inhibiting tumour immunity and promoting tumour progression, and targeting these cells may enhance the efficacies of ICI immunotherapies in NSCLC." (PMID 38115703, 2023). "This suggests that SPP1 is an important pathway that may be associated with tumor progression." (PMID 35812372, 2022). "Furthermore, epithelial cells from cancerous tissues showed preferential expression of ITGB1 and CD44, which have been reported to be linked to tumor progression and could act as a receptor for SPP1." (PMID 36612160, 2022). "Apart from SPP1′s beneficial roles in wound healing and bone homeostasis, SPP1 is considered to be involved in several pathophysiological processes including cancer progression and metastasis, acting as a cardinal mediator of tumor-associated inflammation, as well as immunomodulation." (PMID 35884419, 2022). "For example, early upregulation of cluster 2 proteins such as SPP1 may represent a specific matrix remodelling programme associated with initial fibroblast trans-differentiation into CAFs that accelerates tumour progression during the early stages of transformation." (PMID 35933466, 2022). "Finally, collagen and associated signaling molecules, including ITGB1, YBX1, SPP1 and NF-κB in tumor tissues, could serve as potential biomarkers to monitor tumor progression and predict chemoresistance." (PMID 34758833, 2021). "After SPP1+ TAMs are activated, they are strategically enriched in the tumor core and tumor marginal area to play their functions." (PMID 41751193, 2026). "Differential gene expression confirmed elevated levels of MIF, CD74, CD44, and SPP1 in tumor tissues, while pathway enrichment analyses highlighted cytokine signaling, antigen presentation, and chemokine-regulated immune modulation as key biological processes." (PMID 41683916, 2026). "In the interaction between fibroblasts and macrophages, the macrophage subpopulation supporting tumor angiogenesis exhibits significant activity in ER+BC, with the associated SPP1 and GRN pathways strongly influencing tumor progression." (PMID 41635010, 2026). "In vivo, anti-SPP1 therapy induced a macrophage phenotype switch and significantly reduced tumor burden." (PMID 42020397, 2026). "Collectively, the diverse sub-populations, particularly the immunosuppressive SPP1 + macrophages regulated immune suppression status within tumor microenvironment and represented a potential therapeutic target for DLBCL patients." (PMID 41869451, 2026). "First, we describe important subpopulations of profibrotic and pro-tumor macrophages, including SPP1+, MERTK+, TREM2+, and MARCO+ cells, using high-resolution spatial and single-cell omics technologies." (PMID 41939908, 2026).